C1QA (complement C1q A chain)
Diseases named in the same sentence as C1QA in open-access papers (continued):
Sharing a sentence is not in itself a finding about the gene and the disease.
retinal degeneration (3 papers, 2018 to 2023). Degeneration of the retina. "We also found that in miR-223-null CD11b+ cells from the retina, there was increased C1qa which is associated with progressive retinal degeneration, as well as increased Stat3, also associated with retinal disease." (PMID 32671067, 2020). "Classical complement pathway knockout mice (C1qa−/−) and WT were exposed to photo-oxidative damage to assess independently the functional significance of C1qa (classical pathway) on retinal degeneration." (PMID 30126455, 2018).
sarcopenia (3 papers, 2024 to 2025). Progressive decline in muscle mass due to aging which results in decreased functional capacity of muscles. "Among them, MYH8, HOXB2, C1QA, CDKN1A, and SLC38A1 are associated with sarcopenia, and in this study, LGR5, SERPINA5, and TPPP3 genes were found to be associated with Sarcopenia for the first time." (PMID 38229116, 2024). "In patients with sarcopenia, the expression of TPPP3, C1QA, LGR5, MYH8, and CDKN1A genes are upregulated, and the expression of SLC38A1, SERPINA5, and HOXB2 genes are downregulated." (PMID 38229116, 2024).
skin cutaneous melanoma (3 papers, 2019 to 2022). "In this study, survival analysis showed higher expression level of HLA class II co-expressed genes, especially APOL3, CD74, C1QA and C1QB, were associated with better prognosis in cutaneous melanoma." (PMID 31212865, 2019). "However, the effect of C1QA, C1QB, and C1QC expression on tumour immunity and prognosis of cutaneous melanoma remains unclear." (PMID 36110204, 2022).
viral infection (3 papers, 2021 to 2023). "We, and others, have previously shown that peripheral viral infection is associated with glial activation, and increased expression of genes such as Tnf, Il1a and C1qa by microglia in response to peripheral inflammation has been shown to affect other glial subsets." (PMID 37596606, 2023). "Additionally, TCN2 and C1QA showed predominant expression in macrophages, suggesting the involvement of macrophage activation in viral infection." (PMID 37942334, 2023).
Alzheimer disease (2 papers, 2017 to 2022). A progressive, neurodegenerative disease characterized by loss of function and death of nerve cells in several areas of the brain leading to loss of cognitive function such as memory and language. "In the brain, Alzheimer’s disease and memory-related genes (Camk2n1, Apod, and Serpina3n), and immune-response-related genes (Spp1, CD68, GFAP, Mpeg, Ddx3y, Lyz2, CTSZ, Tyrobp, C4b, and C1qa), were selected for mRNA qPCR analysis in adenine-induced CKD mice." (PMID 35447931, 2022).
Anxiety (2 papers, 2022 to 2023). Intense feelings of nervousness, tension, or panic often arise in response to interpersonal stresses. "In terms of documented links with anxiety, literature mining revealed a robust positive relationship between C1qa and anxiety, where increased C1qa expression is associated with more anxious phenotypes." (PMID 36364936, 2022). "Collectively, we identify C1qa as a potential candidate biomarker of long-term CR linked to phenotypic reductions in anxiety." (PMID 36364936, 2022). "For example, we identified downregulated C1QA expression, a gene with documented links with anxiety-like behavior, ostensibly through its role in inflammation, and Alzheimer’s disease, through its role in synapse elimination and neuronal damage." (PMID 38094940, 2023). "The downregulated expression of C1qa by long-term CR and its extracellular location as a secretory protein flag C1qa as a potential biomarker of CR mediated changes to anxiety and depression." (PMID 36364936, 2022). "Furthermore, text mining highlighted the positive involvement of C1qa in anxiety, depression, neurodegeneration, stress, and ageing, collectively identifying a suitable biomarker candidate for CR." (PMID 36364936, 2022). "Interestingly, C1qa has largely a positive relationship (regulation, expression, quantitative change) with anxiety, stress and depression, collectively yielding a high confidence score (10 mined sentences)." (PMID 36364936, 2022).
astrocytoma (2 papers, 2025). "Comparison of the grade 3 astrocytoma to the matched normal sample, revealed the top three DEGs encoding ECM glycoproteins (NTN1, AEBP1 and SPARC) and ECM-affiliated factors (C1QA, LGALS9 and C1QL1)." (PMID 41366031, 2025).
Cirrhosis (2 papers, 2024 to 2025). A chronic disorder of the liver in which liver tissue becomes scarred and is partially replaced by regenerative nodules and fibrotic tissue resulting in loss of liver function. "Finally, our scRNAseq analysis shows the presence of DAMs in the liver of NAFLD patients, which share the same phenotype, including expression of TREM2, CD9, GPNMB, MHCII (HLA-DRB1), C1QA, and CLEC10A, as those found in the livers of patients with NASH and cirrhosis." (PMID 38280848, 2024).
diabetic nephropathy (2 papers, 2023 to 2025). "Our study explored the same platform GEO dataset for diabetic nephropathy bioinformatics analysis and identified eight potential key genes (TYROBP, ITGB2, CD53, IL10RA, LAPTM5, CD48, C1QA, and IRF8), screened eight transcription factors, and identified 93 miRNA nodes." (PMID 37113991, 2023).
endometriosis (2 papers, 2023 to 2025). The growth of functional endometrial tissue in anatomic sites outside the uterine body. "Multi-omics analysis revealed a positive correlation between expression of central complement factors (C1S, C1QA, C1R, C3) and tissue factor (TF), indicating cross-interaction between complement and coagulation systems in the pathogenesis of endometriosis." (PMID 41488658, 2025). "Multi-omics analysis has revealed that up-regulated expression of complement (C1S, C1QA, C1R and C3) was positively correlated with tissue factor in endometriosis." (PMID 38012607, 2023). "Transcriptomic analysis revealed increased expression of all three C1q genes (C1QA, C1QB, C1QC) in all endometriosis histotypes compared to healthy endometrium, with correlation between expression level and disease severity." (PMID 41488658, 2025).
follicular lymphoma (2 papers, 2012 to 2023). Follicular lymphoma is a form of non-Hodgkin lymphoma characterized by a proliferation of B cells whose nodular structure of follicular architecture is preserved. "Moreover, polymorphisms in the C1qA gene were found to affect the clinical response and duration of response to Rituximab therapy for follicular lymphoma." (PMID 37907575, 2023). "A previous study of 133 patients with follicular lymphoma was done on the same C1qA." (PMID 22897949, 2012).
glioblastoma (2 papers, 2025). The most malignant astrocytic tumor (WHO grade IV). "Glioblastoma patients exhibited significant upregulation of CD29, CD44, CD81, CD146, CqQA, and histone H3 compared to healthy volunteers, with additional upregulation of C1QA, CD44, and histone H3 observed to those with stable disease." (PMID 41373835, 2025).
head and neck squamous cell carcinoma (2 papers, 2019 to 2020). A squamous cell carcinoma that arises from any of the following anatomic sites: lip and oral cavity, nasal cavity, paranasal sinuses, pharynx, larynx, and salivary glands. "LOC51089, also called C1QA, was found to be involved in the innate immune system and was associated with the expression of PD-L1, and its abnormal expression in tumor tissues was confirmed in head and neck squamous cell carcinoma and clear cell renal cell carcinoma." (PMID 33381521, 2020). "Interestingly, all five of these genes, CD74, C1QB, FCER1G, TYROBP, and C1QA are part of a protein-protein interaction network comprised of 20 proteins in total that are found only in head and neck squamous cell carcinomas but not in normal head and neck specimens." (PMID 31139325, 2019).
hepatocellular carcinoma (2 papers, 2022 to 2025). A malignant tumor that arises from hepatocytes. "Meanwhile, Mφ_APOE cluster, preferentially enriched in tumor tissue, was similar to tumor-associated macrophages (TAMs) in hepatocellular carcinoma (HCC) and the lipid-associated macrophages in adipose tissue by expressing APOE, TREM2, C1QA, and GPNMB30,31." (PMID 35999201, 2022).
Hypertension (2 papers, 2015 to 2023). The presence of chronic increased pressure in the systemic arterial system. "The loss of C1QA would also reduce hypertension-induced β-catenin signaling, proliferation of vascular smooth muscle cells, and pathological arterial remodeling." (PMID 36845383, 2023). "Macrophage depletion and C1qa gene deletion attenuated the hypertension-induced β-catenin signalling, proliferation of VSMCs and pathological arterial remodelling." (PMID 25716000, 2015).
influenza (2 papers, 2014 to 2021). An acute viral infection of the respiratory tract, occurring in isolated cases, in epidemics, or in pandemics; it is caused by serologically different strains of viruses (influenzaviruses) designated A, B, and C, has a 3-day incubation period, and usually lasts for 3 to 10 days. "Taken together, these data indicate that deficiencies in C1qa and factor B tended to enhance the susceptibility to IAV and acute pneumococcal OM following influenza." (PMID 24740152, 2014). "Although multiple models have demonstrated that complement activation occurs in influenza, IAV also evades complement by blocking the classical complement pathway through the M1 protein interacting with C1qA." (PMID 34446527, 2021).
lymphoma (2 papers, 2012 to 2023). A malignant (clonal) proliferation of B- lymphocytes or T- lymphocytes which involves the lymph nodes, bone marrow and/or extranodal sites. "The frequency of the C1qA[276A] allele among all patients with lymphoma was 0.48, whereas the frequency of the C1qA[276G] allele was 0.52." (PMID 22897949, 2012). "It is unclear exactly how C1qA polymorphism affects the lymphoma responses to R-CHOP chemotherapy." (PMID 22897949, 2012).
memory impairment (2 papers, 2017 to 2022). "In addition, in viral encephalitis mediated memory impairment, C1qa was upregulated, and mice deficient in either C3 or C3a receptor had reduced synaptic terminal loss." (PMID 28715462, 2017).
meningioma (2 papers, 2018 to 2025). A generally slow growing tumor attached to the dura mater. "Interestingly, C1QA complement component has been recently reported as overexpressed in WHO I and II meningiomas." (PMID 29662628, 2018).
myopia (2 papers, 2017 to 2023). "Previous studies have reported the upregulation of the complement pathway, including C1q, C1qa, C2 and C1qb during the development stages of myopia in guinea pigs and chicks." (PMID 37448698, 2023). "A diverse range of complement-related genes were differentially-expressed, with components and regulators of both the classical and alternate pathways up-regulated in late myopia (CS1, PROS1, C1QB and CFD) and late hyperopia (SERPING1, C1QA, CRP, C7 and CFD)." (PMID 28852117, 2017).
Nephropathy (2 papers, 2025). A nonspecific term referring to disease or damage of the kidneys. "In addition to elevated levels of prothrombotic factors such as tissue factor (F3), fibrinogen α chain (Fga) and Pai1 gene expression, complement activators C3, C1qa, and C5ar1 were upregulated in adenine‐ and folic acid‐induced nephropathy." (PMID 41324413, 2025).
Obesity (2 papers, 2020 to 2023). Accumulation of substantial excess body fat. "In the diet-induced obesity mouse model, C1qA was necessary to cause damage to cerebral vasculature and white matter." (PMID 36845383, 2023). "Furthermore, obesity-induced microglia phagocytosis and breakdown of myelin in the corpus callosum were also prevented by deficiency of C1QA." (PMID 32273396, 2020). "However, no changes in MBP levels were found in brain sections of WD-fed C1qa KO compared with CD-fed WT and C1qa KO mice, indicating that deficiency of C1QA prevented the obesity-induced degradation of myelin." (PMID 32273396, 2020). "In our study, to assess the role of C1QA in WD-induced obesity, we chose to focus on cerebrovascular and white matter structures as well as microglia activity based on findings from two previous studies." (PMID 32273396, 2020). "However, in this study, obesity-induced cerebrovascular damage and white matter loss was prevented by C1QA deficiency without altering the weight and metabolic profiles of these mice which were similar to the WD-fed WT mice." (PMID 32273396, 2020).
pulmonary fibrosis (2 papers, 2017 to 2022). Chronic progressive interstitial lung disorder characterized by the replacement of the lung tissue by connective tissue, leading to progressive dyspnea, respiratory failure, or right heart failure. "C1qa, Fcgr1, C1qb, C1qc, Ccr5, Slc11a1, Aif1, Emr1 and Cxcl10 were identified as the most closely connected module which were highlighted in yellow, including 9 nodes and 32 edges, and the genes in this region were upregulated in pulmonary fibrosis." (PMID 35078421, 2022).
age-related hearing loss (1 paper, 2014). "We also screened for C1qa playing a protective role in age-related hearing loss in the congenic D2.B6-C1qa model and found that a lack of C1qa does not prevent this condition." (PMID 24804771, 2014). "We next determined if a lack of C1qa expression would protect mice from progressive or age-related hearing loss (AHL) in two different mouse models." (PMID 24804771, 2014).
amyloid (1 paper, 2023). "These genes, Thy1, Gfap, Tyrobp, Ctsd, Cst7, C1qb, Lyz2, Ctss, Trem2, Mpeg1, Hexb, Cd68, C1qb, C1qa, Ctsz, Grn, Laptm5, B2m, C1qc, Hexa, and Serpina3n, were increased in the 7-month-old 5XFAD model in the cortex and associated with amyloid plaque image patterns." (PMID 38036733, 2023).
Apathy (1 paper, 2025). Apathy is a quantitative reduction of interest, motivation and the initiation and persistence of goal-directed behavior, where often the accompanying emotions, thoughts, and social interactions are also diminished. "Composite apathy scores were strongly and positively correlated with mRNA fold changes for all examined genes: Tyrobp, Trem2, C1qa, C1qb, C1qc, C3, C3ar1, and Cd33 (p < 0.0001)." (PMID 41377997, 2025).
autism (1 paper, 2024). Persistent deficits in social interaction and communication and interaction as well as a markedly restricted repertoire of activity and interest as well as repetitive patterns of behavior. "Six genes were significantly differentially expressed between autism likelihood (social communication) groups: CYSLTR2, NOX1, C1QA, CXCL10, C8A, IL23R (all up-regulated, p < 0.05)." (PMID 39247132, 2024).
brain inflammation (1 paper, 2023). "Co-expression analysis suggested a positive correlation between the age-dependent increase in Apoe and Apoj and the expression of Gfap and C1qa, which are known to increase during brain inflammation." (PMID 37705104, 2023).
breast tumors (1 paper, 2024). "In our study, we revealed that Cd68+ApoE+ cells were found in the TMEs of lung metastatic breast tumors were correlated with C1qa/b/c, Cd74, and ApoE expression." (PMID 39695088, 2024).
cavernous hemangioma (1 paper, 2022). A hemangioma characterized by the presence of cavernous vascular spaces. "Among all types of cells in the cavernous hemangioma, only m2Maph highly expressed C1QA, C1QB, and C1QC, which provided a deeper understanding of the origin and functions of C1q in the immune responses." (PMID 35865633, 2022).
Cognitive impairment (1 paper, 2023). Abnormal cognition is characterized by deficits in thinking, reasoning, or remembering. "Some genes (C3, C1QA) about complement cascade play an important role in synapse refinement during brain development, but aberrant upregulation and deposition of complement will lead to synapse loss and cognitive impairment." (PMID 37333458, 2023).
congenital cataracts (1 paper, 2023). "We identified 18 HUB genes, among which four core genes, C1qa, C1qb, C1qc, and Cd74, were closely related to congenital cataracts induced by Crim1 mutation." (PMID 36586009, 2023). "In conclusion, through comprehensive biological analysis of the GSE62561 gene expression profile, a total of 750 DEGs were identified, of which C1qa, C1qb, C1qc, and Cd74 may be related to the occurrence and development of congenital cataracts caused by Crim1 mutations." (PMID 36586009, 2023). "In this study, the C1qa, C1qb, and C1qc genes were upregulated in mutant mice, suggesting that the early development of congenital cataracts may activate the classical complement system, leading to synaptic disorders and neurodegenerative diseases, thus promoting the development of CC." (PMID 36586009, 2023). "In addition, some researchers have found that the pathogenesis of congenital cataracts caused by TDRD7 deficiency may be related to the immune response, defence response, and related genes LY86, C1QA, C1QB, and C1QC." (PMID 36586009, 2023).
cryptococcal infection (1 paper, 2022). "In particular, of the top 10 genes with the largest change in response to cryptococcal infection, three are components of the classical complement activation pathway: C1qb, C1qa, and C1qc." (PMID 35628686, 2022).
epilepsy (1 paper, 2015). A brain disorder characterized by episodes of abnormally increased neuronal discharge resulting in transient episodes of sensory or motor neurological dysfunction, or psychic dysfunction. "Also little is known about the specific functional implications of the downregulated complement factors C1qa (0.88-fold) and Cr1l (0.91-fold) in epilepsy." (PMID 26684451, 2015).
esophageal squamous cell carcinoma (1 paper, 2023). Esophageal squamous cell carcinoma (ESCC) is a type of esophageal carcinoma (EC) that can affect any part of the esophagus, but is usually located in the upper or middle third. "We analyzed two single-cell RNA sequencing (scRNA-seq) datasets (GSE145370 and GSE160269) of esophageal squamous cell carcinoma to identify a novel TREM2-positive TAM subpopulation characterized by upregulation of TREM2, C1QC, C1QB, C1QA, SPP1, and APOE." (PMID 37187751, 2023).
gout (1 paper, 2021). A condition characterized by painful swelling of the joints, which is caused by deposition of urate crystals. "The ROC curve showed that the serum levels of C1QA and C1QB predicted the status of primary gout with middle accuracy (C1QA: AUC = 0.812, p < 0.001; C1QB: AUC = 0.817, p < 0.001)." (PMID 34603204, 2021).
Hearing impairment (1 paper, 2014). A decreased magnitude of the sensory perception of sound. "We further demonstrate that C1qa expression is not necessary for normal hearing in mice but the lack of expression of H2-Kb and H2-Db causes hearing impairment." (PMID 24804771, 2014).
hearing loss (1 paper, 2014). "We hypothesized that C1qa synaptic re-expression in aging might mediate AHL and that a lack of C1qa expression in our C1qa−/− mice might protect against age-related hearing loss and OHC death." (PMID 24804771, 2014).
Hepatic fibrosis (1 paper, 2021). The presence of excessive fibrous connective tissue in the liver. "The activated complement pathway may play a inhibitory role in hepatic fibrosis through activation of the C1 complex (C1qrs) triggered by antigen–antibody complexes, because complement pathway activation is required for the upregulation of many proteins, such as C1QA." (PMID 33933138, 2021).
HIV-1 infection (1 paper, 2024). The type species of lentivirus and the etiologic agent of acquired immunodeficiency syndrome (AIDS). "Upregulated C1QA, CD163, and CXCL16 and downregulated LMNA and CLU were identified as age-associated genes tied to HIV-1 infection." (PMID 38399364, 2024).
Insulin resistance (1 paper, 2017). Increased resistance towards insulin, that is, diminished effectiveness of insulin in reducing blood glucose levels. "C1qa expression has been shown to be elevated in visceral adipose tissue from obese patients and its deficiency protects mice from HFD-induced insulin resistance." (PMID 28752050, 2017).